ARF6 (ARF GTPase 6)
Diseases named in the same sentence as ARF6 in open-access papers (continued):
Sharing a sentence is not in itself a finding about the gene and the disease.
pancreatic cancer (continued). "Ferroptosis can be induced by inhibiting ADP ribosylation factor 6 (ARF6) to activate active fatty acid synthase 4(ACSL4), thereby overcoming gemcitabine resistance in pancreatic cancer." (PMID 40866937, 2025). "To analyze the suitability of model cells for the follow-up experiments, we investigated two different human pancreatic cancer cell lines for their DUSP6 and ARF6 expressions." (PMID 36017891, 2022). "Studies have shown that ARF6 is highly expressed in pancreatic cancer cell lines PANC1 and PANC2, and the inhibition of ARF6 can promote RSL3-induced ferroptosis." (PMID 36499358, 2022). "DUSP6 can not only act as a tumor suppressor in pancreatic cancer, but also as a vital intermediate molecule in our positive feedback loop composed of ERK1/2, ARF6 and DUSP6." (PMID 36017891, 2022). "DUSP6 can act not only as a tumor suppressor in pancreatic cancer, but also as a vital intermediate molecule in our positive feedback loop composed of ERK1/2, ARF6 and DUSP6." (PMID 36017891, 2022). "Previous studies showed that ARF6 is a downstream factor in the Kras/ERK signaling pathway and promotes proliferation and the Warburg effect in pancreatic cancer cells." (PMID 34621682, 2021). "The AUCs of WASF2,ARF6,SNORA74A, and SNORA25 in serum from patients in the early stages of pancreatic cancer (stages 0, I, and IIA) were > 0.9, compared with an AUC of 0.93 for the level of CA19‐9." (PMID 30358104, 2019). "The enhancement of the ARF6-based pathway and its activation by external ligands may promote tumor cell motility, PD-L1 dynamics, and IEV of pancreatic cancer." (PMID 35991554, 2022). "In a previous study, ARF6 was found to be a member of the Ras superfamily, which is induced by the KRAS-ERK1/2 pathway and promotes pancreatic cancer development by satisfying the increased energy needs and biosynthetic requirements of uncontrolled cell growth." (PMID 36017891, 2022). "The results of this study suggest that WASF2,ARF6,SNORA74A, and SNORA25 may be useful tools for the early detection of pancreatic cancer." (PMID 30358104, 2019). "Meanwhile, a negative correlation between ARF6 and ACSL4 expression was also confirmed in tissue specimens from pancreatic cancer patients." (PMID 37580745, 2023). "Specifically, to elucidate the negative correlations between ARF6 and DUSP6 in pancreatic cancer, we examine their expressions in pancreatic cancer tissues by immunohistochemical staining." (PMID 36017891, 2022). "A clear negative relation was found between ARF6 and DUSP6 in pancreatic cancer patients." (PMID 36017891, 2022). "Further experiments have confirmed that ARF6 does not directly affect lipid peroxidation, but shapes the cell lipid components into a state that is easy to oxidize by regulating the level of ACSL4 protein, and finally induces lipid peroxidation and inhibits pancreatic cancer cell growth." (PMID 34503532, 2021).
melanoma (25 papers, 2009 to 2026). A malignant, usually aggressive tumor composed of atypical, neoplastic melanocytes. "Although stable expression of ARF6-T27N has been shown to affect tumor cell invasion, it does not alter the cell cycle progression because it caused only a small increase in the number of cells in the G2-M phase in melanoma cells." (PMID 27391262, 2016). "Hence, these data suggest that targeting ARF6 may render melanomas with resistance mutations more vulnerable to MAPK inhibitors." (PMID 40909781, 2025). "In a genetically engineered model of aggressive melanoma, tumor-specific Arf6 deletion attenuated BRAFV600E protein expression and MAPK signaling and prevented rapid tumor progression." (PMID 42050077, 2026). "In pursuit of this, we interrogated human melanoma cells and found that doxycycline-induced, ectopically expressed ARF6-GTP, in the form of ARF6Q67L, or adenoviral delivered ARF6Q67L, augmented endogenous BRAFV600E expression in human melanoma cells." (PMID 40909781, 2025). "Consistent with this, ARF6 silencing led to significantly reduced viability in multiple human melanoma cell lines." (PMID 40909781, 2025). "Proteomic clues to ARF6-mediated survival were evident in murine melanoma cell lines cultured in full serum." (PMID 40909781, 2025). "ARF6 is a GTPase that regulates N-Cadherin-associated CTNNB1, resulting in its sequestration or liberation and subsequent relocation to the nucleus in melanoma cells." (PMID 38854152, 2024). "WNT5A binds to Frizzled 4-LRP6 complex to activate ARF6, which leads to the separation of β-catenin and N-cadherin, resulting in free β-catenin into nucleus, and ultimately promotes the metastasis of melanoma cells." (PMID 37716993, 2023). "The role of phosphoinositides, particularly PIP3, in regulating leading edge formation or protrusion activity has been extensively reported, including ARF6 being a driver of PI3K enrichment in melanoma cell protrusions." (PMID 33712589, 2021). "One pro-invasive pathway ARF6-PI3K-AKT indicates a role for ARF6 in mediating the melanoma metastatic cascade, since aberrant activation of ARF6 leads to reduced survival in human melanoma patients." (PMID 33807778, 2021). "In this context, ARF6 disrupts N-cadherin and β-catenin complexes, weakening adherens junctions, in order to regulate melanoma invasiveness and promote pulmonary metastasis." (PMID 33072757, 2020). "As expected, WNT5A activates ARF6 also in melanoma, controlling the shuttling of β-catenin between the plasma membrane and cytoplasm." (PMID 33072757, 2020). "The role of Arf6 in several pathways related to melanoma dissemination has been extensively explored, and there is evidence that this protein also contributes for the lymphangiogenesis process occurring under physiological and pathological conditions." (PMID 33072757, 2020). "Previous studies found that WNT/β-catenin signaling stimulate cell invasion and metastasis via ARF6 in melanoma cells." (PMID 33928018, 2020). "Particularly, Arf6 role on melanoma progression and tumorigenesis is mediated by Ras/RAF/MEK/ERK signaling pathway, which activates Rac1, leading to cytoskeleton remodeling and the formation of invadopodia." (PMID 33072757, 2020). "Recently ARF6 has been found to be a major signaling node in GNAQ mutant melanoma, and blockade of ARF6 has been shown to inhibit multiple pathways activated in uveal melanoma." (PMID 31320995, 2019). "We found that Tris DBA palladium inhibits ARF6 activation in a dose dependent manner in GNAQ mutant melanoma cells." (PMID 31320995, 2019). "WNT-5A activates ARF6 in melanoma cells leading to disruption of N-cadherin-β-catenin interaction, enhanced β-catenin-mediated transcription and invasion." (PMID 26514730, 2016). "The activity of the GEF GEP100, stimulated downstream of Wnt5a binding to Fzd4 and LRP6, promoted ARF6 activity and subsequent metastasis in a melanoma xenograft model." (PMID 27589803, 2016).
melanoma (continued). "Intriguingly, it was recently reported that Wnt5a activates Arf6, leading to the disruption of N-cadherin/β-catenin complexes, and increased melanoma cell invasion." (PMID 25779663, 2015). "In an in vivo study investigating ARF6 expression, melanoma growth and metastasis, ARF6 was shown to reduce tumour growth but significantly increased the invasive capacity of the tumour cells." (PMID 26185744, 2015). "Arf6 expression was suppressed in A2780 ovarian carcinoma cells and A375-SM malignant melanoma cells, which both use α5β1, αVβ3, and syndecan-4 to engage fibronectin, and in both cell lines Arf6 inhibition blocked recycling of α5β1 but not αVβ3." (PMID 23453597, 2013). "Because ARF6 activation significantly reduced tumor cell death after MAPKi, we asked whether inhibition of ARF6 could sensitize melanoma to clinically acquired or innate MAPKi resistance." (PMID 40909781, 2025). "Activation of ARF6 failed to alter BRAF mRNA levels in A375 melanoma cells, which harbor a homozygous BRAFV600E mutation, demonstrating that ARF6-mediated upregulation of BRAFV600E occurred without altering BRAF oncogene expression." (PMID 40909781, 2025). "Inhibitors against this pathway could be used to target RAS driven melanoma, since ARF6 may have control over RAS." (PMID 33807778, 2021). "Indeed, Arf6 can modulate distinct molecular networks essential for early and late stages of melanoma metastasis." (PMID 33072757, 2020). "Additionally, ARF6 ectopic expression reduces tumor growth and increases the invasive ability of melanoma cells in an immunocompromised mouse model." (PMID 33072757, 2020). "Similarly, Arf6 overexpression increases metastatic disease burden, accelerating melanoma metastasis and lung colonization in an immunocompetent mouse model." (PMID 33072757, 2020). "Additionally, the ectopic expression of the constitutively active form of ARF6 (ARF Q67L) enhances melanoma progression and metastasis in vivo." (PMID 32426352, 2020). "Currently, among Arfs, only Arf6 was reported as playing a critical role in melanoma." (PMID 33072757, 2020). "Melanoma provides a prominent example for the role of Wnts and ARF6 in tumor invasion." (PMID 27589803, 2016). "Additionally, canonical signaling through Wnt5a has been shown to promote ARF6 activation and subsequent melanoma invasion by stimulating β-catenin-mediated transcriptional activity." (PMID 27589803, 2016). "In human melanoma cells, pharmacologic inhibitors of BRAFV600E uniformly induced swift activation of ARF6, driving a positive feedback loop that restored MAPK-driven anti-apoptotic signaling and supported drug-tolerant survival and growth." (PMID 42050077, 2026). "Consistent with genetic activation of ARF6, pharmacological activation of ARF6 with QS11, an inhibitor of ARF GTPase Activating Protein 131, increased BRAFV600E protein expression in human melanoma, colorectal carcinoma and glioma cell lines." (PMID 40909781, 2025). "In patient-derived melanoma cells with innate or clinically acquired resistance to MAPK inhibitors, ARF6 inhibition enhanced sensitivity to combined BRAF + MEK inhibition." (PMID 40909781, 2025). "For example, we have previously shown that ARF6-GTP upregulated PI3K expression and AKT-signaling in melanoma while inhibition of ARF6 reduced PI3K and AKT activation." (PMID 40909781, 2025). "Consistently, silencing of Arf6 downregulated BRAFV600E and p-MEK detection in murine melanoma cells." (PMID 40909781, 2025). "In melanoma, Wnt5a promotes tumor cell proliferation by activating ADP-ribosylation factor 6 (ARF6) through interaction with FZD4 or LRP6, which in turn facilitates β-catenin nuclear translocation." (PMID 40399946, 2025). "In melanoma cells, the stimulation of WNT5A, a member of the Wnt signaling pathway, induces ARF6 activation mediated by BRAG2, which facilitates the release of β-catenin from cadherin and stimulates tumor cell invasion." (PMID 32426352, 2020).
melanoma (continued). "Despite the difficulties related with the measurement of Arf6 activation state due to GTP instability, the aberrant activation of this protein was confirmed in human melanoma samples compared with matched normal skin tissue." (PMID 33072757, 2020). "In melanoma cells, WNT-5A activates small GTPase ADP-ribosylation factor 6 (ARF6) via FZD4-LRP6 binding." (PMID 26514730, 2016). "Although the proposal that Wnt5a increases cell migration is compatible with its capacity to increase Arf6 activity in melanoma cells, we have limited knowledge concerning regulation of Wnt5a expression by EGF/Arf6 signaling in gastric cancer cells." (PMID 25779663, 2015). "Furthermore, in patient-derived melanoma xenografts with innate or clinically acquired resistance to MAPK inhibitors, ARF6 silencing alone significantly suppressed tumor growth in vivo." (PMID 42050077, 2026). "To test whether ARF6 activation could protect against apoptosis, we deployed a doxycycline-inducible system to express either ectopic ARF6Q67L or ARF6WT in human melanoma cells." (PMID 40909781, 2025). "In addition, Arf6 has also been reported to regulate tumor cell invasion and migration via the ERK signaling pathway, and to promote melanoma cell invasion and metastasis by enhancing ERK1/2 phosphorylation." (PMID 32822124, 2020). "For example, MV shedding is inhibited in various tumor cell lines (including human melanoma, colon cancer, prostate adenocarcinoma and breast tumor cell lines) where the GTP-binding protein ARF6 activation is inhibited; ARF6 regulates plasma membrane endosomal trafficking." (PMID 30895170, 2019). "ARF6-dependent survival may also help explain why tumor-specific deletion of Arf6 significantly diminished tumor development and progression in BRAFV600E PTENWT melanoma models." (PMID 40909781, 2025). "Hence, our overall data supports that ARF6 is activated in the early phases of adaptive resistance, acutely responding to diminished MAPK signaling, and facilitating the survival of drug-tolerant persister cells in melanoma." (PMID 40909781, 2025). "Moreover, Arf6 was described to increase PI3K protein levels and be sufficient and indispensable for PI3K/Akt activation, kinases that are mainly located in peripheral cellular compartments and induce melanoma invasion." (PMID 33072757, 2020).
hepatocellular carcinoma (16 papers, 2012 to 2026). A malignant tumor that arises from hepatocytes. "Overall, these results demonstrated that ARF6 contributed to the migration, invasion and metastasis of hepatocellular carcinoma cells, which is associated to the activation of MAPK signaling." (PMID 35140331, 2022). "Meanwhile, our data supported the concept that EGF is capable of inducing ERK and Rac1 activation through the Arf6 pathway, and this process is associated with hepatoma cell migration where GEP100 was present." (PMID 22701712, 2012). "The phosphorylation of ACAP4Y843 promoted ARF6-GTPase activity and hepatoma cell migration, which was consistent with the findings in HCC tissues." (PMID 39744421, 2025). "JAK1 activation phosphorylates ACAP4 at Tyr843, thereby increasing ARF6-GTPase activity to promote hepatoma cell migration and HCC metastasis." (PMID 39744421, 2025). "IL6 then activates JAK1 to phosphorylate its downstream effector ACAP4 at Tyr843, a novel phosphorylation site identified in this context, which in turn promotes ARF6-GTPase activity and hepatoma cell migration." (PMID 39744421, 2025). "These outcomes are aligned with prior investigations reporting the prognostic value of ARF6 in other malignancies, such as renal cancer and hepatocellular carcinoma." (PMID 40275490, 2025). "During IL6-induced JAK1 signaling in tumor cells, we identified a novel phosphorylation site of ACAP4 at Tyr843 that facilitates hepatoma cell migration by increasing ARF6-GTPase activity." (PMID 39744421, 2025). "To study the clinical significance of ARF6 in hepatocellular carcinoma, we analyzed the level of ARF6 in HCC patients with Online Oncomine dataset." (PMID 37716993, 2023). "Our results reveal that the DDR1/PSD4/ARF6 signaling axis acts as an important inducer in the regulation of the migration, invasion and lung metastasis of hepatocellular carcinoma cells by collagen induced DDR1 signaling." (PMID 35140331, 2022). "To examine the effect of ARF6 on the migration and invasion of hepatocellular carcinoma cells in vitro, we performed wound healing assay, trans-well migration and invasion assay." (PMID 35140331, 2022). "In our study, we showed that ARF6 promotes the migration, invasion and lung metastasis of hepatocellular carcinoma cells." (PMID 35140331, 2022). "DDEFL1 is related to maintaining a limiting amount of ARF6 in GTP-loaded form by accelerating its GTP hydrolysis activity, which has been implicated in hepatocellular cancer pathogenesis and lung cancer development." (PMID 29348842, 2017). "Taken together, this study highlights the function of the PH domain of GEP100 and its regulated Arf6/ERK/Rac1 signaling cascade in EGF-induced hepatoma cell migration." (PMID 22701712, 2012). "Our results demonstrate that EGF stimulates hepatoma HepG2 cell migration through GEP100-dependent activation of the Arf6/ERK/Rac1 signaling pathway." (PMID 22701712, 2012). "Moreover, the increased expression of ARF6-CD147 signaling components, like Cytohesin 2/ARNO, an ARF6 GEF and Rac1 were associated with poor overall survival of hepatocellular carcinoma patients." (PMID 32426352, 2020). "We wished to examine whether Arf6 influenced cell migration in hepatoma cells after EGF treatment." (PMID 22701712, 2012). "Collectively, these mechanisms allow circ0001955 to restore the carcinogenic activity of ARF6, SPATS2, TRAF6, and MAPK11 in chronically HCV-infected hepatocytes, promoting the initiation and progression of hepatocellular carcinoma." (PMID 41465470, 2025). "One study found that elevated ARF6 promotes hepatocellular carcinoma (HCC) metastasis." (PMID 40270615, 2025). "In this study, we have demonstrated that EFA6B promotes the migration and invasion of hepatocellular carcinoma cells, and is required for DDR1-mediated ARF6 activation." (PMID 35140331, 2022).
hepatocellular carcinoma (continued). "In hepatocellular carcinoma, miR-139-5p can regulate the proliferation, migration and invasion of hepatocellular carcinoma cells by targeting different targets such as SLITRK4, CCT5 and ARF6." (PMID 35386287, 2022). "In this study, the role of Arf6 on CD147 trafficking in liver cancer cells and its contribution to the malignant behaviors of HCC (hepatocellular carcinoma) were examined." (PMID 31752956, 2019). "To investigate the role of Arf6 in HGF-dependent cell functions of hepatocytes, we employed the human hepatocellular carcinoma cell line HepG2 cells as a model system." (PMID 28842595, 2017). "Indeed, we show here that EGF-induced Arf6 activation could be suppressed by ectopic expression with GEP100 siRNA as well as GEP100-△PH, so we suggest that the PH domain of GEP100 is involved in EGF signaling to induce Arf6 activation and migration of human hepatoma HepG2 cells." (PMID 22701712, 2012). "In hepatocellular carcinoma (HCC), type I collagen promotes cancer cell stemness and metastasis through the CD44/DDR1/YAP axis and the PSD4/ARF6 signaling pathway, respectively." (PMID 40563472, 2025). "However, it was found in hepatoma cells that downregulating Arf6 expression suppressed the activity of its downstream effector Rac1 by attenuating the phosphorylation level of ERK1/2, which reduced the invasion and migration of hepatoma cells." (PMID 32822124, 2020).